HPSE (heparanase)
Diseases named in the same sentence as HPSE in open-access papers (continued):
Sharing a sentence is not in itself a finding about the gene and the disease.
cancer (continued). "Therefore, heparin antimetastatic activity is likely mainly related to inhibition of coagulation, heparanase, and P-selectin interactions, avoiding cancer cell activation of the coagulation cascade to recruit a protective layer of platelets, and increase inflammation and angiogenesis." (PMID 32824699, 2020). "Indeed, HPSE inhibitors may result in more harm than benefit in some cancers and may explain why several human trials in the past experienced failures and have since been discontinued." (PMID 33256730, 2020). "The diversity of outcomes attributed to heparanase and the difficulties of unequivocally determining which of these are due to its enzymatic activity is also discussed and leads us to the conclusion that heparanase is a valid, but challenging drug target for cancer." (PMID 31850210, 2019). "Possibly the intracellular location of heparanase may be a prognostic indicator for some cancers." (PMID 31850210, 2019). "Notably, cancer patients exhibiting high levels of heparanase had a significantly shorter postoperative survival time than patients whose tumors exhibit low levels of heparanase, thus supporting its pro-metastatic function." (PMID 29464068, 2018). "Notably, upregulation of heparanase was reported in various cancer types." (PMID 28038446, 2017). "In addition, the HS chain may be shortened or degraded by heparanase (HPSE1/2) to functionally remove growth factor binding sites and affect cancer progression." (PMID 28672878, 2017). "Heparin mimetics designed for specific targets are expected to act preferentially on specific proteins such as growth factors of the FGF family and VEGF, and heparanase, which are overexpressed in cancer, but as was seen with PG545 other activities may well be detected for some of these compounds." (PMID 28974047, 2017). "However, few studies focused on the regulation of heparanase expression in cancer cells." (PMID 26689987, 2016). "Thus, it is reasonable to imply that the methylation regulation mechanism of heparanase may interfere with the binding of these transcription factors, leading to the heparanase expression in different carcinoma stages." (PMID 24632672, 2014). "HPSE is an endoglycosidase involved in HPSGs cleavage, a key component of the ECM, BM, and cell surface proteoglycans, leading to ECM remodeling, which may facilitate the cellular invasiveness associated with cancer metastasis." (PMID 22719918, 2012). "In addition to proteolytic enzymes like MMPs and serine proteases, heparanase, given its ability to degrade HSPGs, may play a role in cancer cell invasion." (PMID 18647407, 2008). "Heparanase 1 (HPSE1) and Heparanase 2 (HPSE2) exhibit opposing expression patterns and functions in pathological contexts, such as cancer." (PMID 40899692, 2025). "A recent study correlated increased HPSE expression with higher immune infiltration levels of CD4+ and CD8+ T cells, macrophages, neutrophils, and dendritic cells in cancer." (PMID 37115924, 2023). "Moreover, heparanase-based anti-metastatic and anti-angiogenic activities of aspirin may contribute to explaining its role as adjuvant treatment in patients already having cancer other than as a primary preventive method." (PMID 37628573, 2023). "As such this has been shown in some cancers for e.g. ESCRT components, syntenin, heparanase, small GTPases (such as Rab27A and Rab27B), SNARE proteins (such as SNAP23)." (PMID 35898875, 2022). "Heparanase (HPSE), a β-D-endoglucuronidase, is the only mammalian enzyme known to cleave HS and is one of the most studied glycosylation-related enzymes in cancer." (PMID 33494442, 2021). "By inhibiting heparanase activity, ASA was found to delay cancer progress (metastasis, angiogenesis) both in vitro and in vivo." (PMID 34073241, 2021). "Here we outlined the remarkable features of HSPGs, such as GPC1, GPC4, GPC5, SDC1, SDC2, SDC3 and HSPG2, and some HSPG-related proteins like heparanase and SULF1/2, in cancer diagnosis." (PMID 34249755, 2021).
cancer (continued). "circHIPK3 can accelerate angiogenesis and cancer metastasis by modulating vascular endothelial growth factor (VEGF), heparanase (HPSE) and other molecules." (PMID 33975598, 2021). "Sugar-based molecules such as heparins or natural heparan sulfate polysaccharides have been developed and widely studied for controlling heparanase (HPSE) enzymatic activity, a key player in extracellular matrix remodelling during cancer pathogenesis." (PMID 34677445, 2021). "Heparanase (HPSE) is an endoglycosidase that cleaves heparan sulfate and has been shown in various cancers to promote metastasis, angiogenesis, osteolysis, and chemoresistance." (PMID 32899927, 2020). "For example, heparanase (HPSE), matrix metalloproteinases, and sulfatases, are highly expressed in many cancers, whereas some heparan sulfate sulfotransferases are silenced." (PMID 32477959, 2020). "For example, HPSE eRNA promotes cancer progression by interfering with the chromatin looping and regulating the hnRNPU/p300/EGR1/HPSE axis." (PMID 33392092, 2020). "FZD8, plasminogen activator, urokinase receptor, ITGA2, WNT2B, TIMP3, WNT5B, FGF5, heparanase, HBEGF and WNT3A were up-regulated in the proteoglycan pathways in cancer, whereas WNT10A, PIK3R3, IGF2 were down-regulated." (PMID 30482199, 2018). "The data provide evidence displaying that increased sulfation degree in HS is not favored by TGF‐β1, highlighting, for the first time, a crosstalk between heparanase, HS, and TGF‐β1 signaling in cancer cells." (PMID 28286736, 2017). "Heparanase (HSPE) is an endoglycosidase that participates in the degradation and remodeling of the HS portion of HSPGs and is overexpressed in many cancer types." (PMID 28672878, 2017). "This devastating loop is efficiently blocked, nonetheless, by the heparanase inhibitors PG545 and Roneparstat, lending hope that these compounds, now in phase I/II clinical trials in cancer patients will prove efficacious also in AP." (PMID 28386074, 2017). "Importantly, two genes associated with improved long term survival, HPSE and RPS9, were identified to be hypomethylated in mammary glands of rats exposed prepuberally to GEN or to GEN + BPA respectively, reinforcing the suggested cancer suppressive properties of GEN." (PMID 28505145, 2017). "Researchers have shown in a myriad of cancer models that PI-88 and PG545 potently inhibit tumor angiogenesis by binding the active site of heparanase, and can be used in combination with other chemotherapeutics or as an adjuvant therapy." (PMID 26891329, 2016). "Malignant cells produce proteolytic enzymes, including serine proteinase, cathepsins, metalloproteinases (MMPs), and heparanase, among which MMP-9 and MMP-2 play key roles in destroying the basement membrane for mediating cancer invasion and metastasis." (PMID 27391337, 2016). "Moreover, exosome secretion from MM cells was shown to be dramatically increased by heparanase whose expression is up-regulated in aggressive cancer cells including MM cells, implying that heparanase may be one of the factors causing elevated secretion of exosomes." (PMID 26950273, 2016). "Some investigations have proved that HPSE is overexpressed in most malignancies, including in HCC, and plays a key role in cancer invasion and metastasis." (PMID 23308126, 2013). "Heparanase expression can be up-regulated by nerve growth factor (NGF) and NGF expression in astrocytes has been shown to be stimulated in response to cancer cell-secreted factors TGF-β1, IL-1β, and bFGF." (PMID 24213237, 2012). "Heparanase (HPA), an endo-h-D-glucuronidase that cleaves the heparan sulfate chain of heparan sulfate proteoglycans, is overexpressed in majority of human cancers." (PMID 22363633, 2012). "When evaluating all cases collectively, blocking antibodies to FGF-2, HB-EGF, heparanase-1, MT1-MMP, SDF-1 and TGF-β1 significantly diminished carcinoma cell growth stimulation and this effect was antibody dose-dependent." (PMID 23056402, 2012).
cancer (continued). "Heparanase is the only human enzyme responsible for heparan sulfate (HS) breakdown, an activity that remodels the extracellular matrix (ECM) and strongly drives cancer metastasis and angiogenesis." (PMID 40940793, 2025). "As hypothesized, heparanase and TLR4 inhibition resulted in reduced capacity of cancer cells to form spheroids, although heparan sulfate itself and TLR4 agonist increased this effect." (PMID 39349458, 2024). "In fact, we demonstrate that the conditioned medium collected from mast cells is able to increase the capability of cancer cells to form mammospheres in a MUC-1/estrogen receptor-dependent manner, and the whole mechanism can be prevented by inhibiting heparanase." (PMID 39349458, 2024). "The effectiveness of Roneparstat in inhibiting the pathologic action of heparanase in vivo has been demonstrated in heparanase-driven processes other than RN, including malignant tumor progression and numerous non-malignant conditions." (PMID 36979689, 2023). "Following its characterization, it did not take very long to realize that heparanase-1 was not only involved in normal HS catabolism within the ECM, but that it was also implicated in cancer and, more precisely, metastasis." (PMID 36680276, 2023). "Hence, cleavage of HS by heparanase not only contributes to disassembly of the ECM, thereby facilitating cancer metastasis, but also affects diverse physiological and pathological processes ranging from gene transcription to DNA damage." (PMID 36980232, 2023). "The heparanase-inhibiting ability of our small dendrimer HS-mimetics has been investigated in various cancers but their efficacy in neuroinflammatory models has not been evaluated." (PMID 37915090, 2023). "Heparanase (HPSE) is a cancer metastasis protein that is regulated by the hnRNPU/p300/EGR1/HPSE axis, promotes high expression of HPSE enhancer RNA, is an independent prognostic factor for poor prognosis in cancer patients." (PMID 37091789, 2023). "Moreover, we investigated HPSE expression in 466 ESCC tissues and paired adjacent normal tissues from 4 cohorts and found it to be significantly lower in these cancer tissues than in the paired adjacent normal tissues." (PMID 35840985, 2022). "Higher levels of pre- and post-treatment heparanase in oestrogen receptor-negative cancers (p = 0.0279 and p = 0.0498, respectively) than in positive ones were noted." (PMID 34070058, 2021). "Although heparin is a heparanase inhibitor, it is not clinically utilized in cancer therapy due to its anti-coagulant effect." (PMID 35118073, 2021). "Heparanase-inhibiting heparin/heparan sulfate-mimicking compounds and neutralizing antibodies are highly effective in animal models of cancer progression, yet none of the compounds reached the stage of approval for clinical use." (PMID 34199150, 2021). "A negative correlation between heparanase expression and cancer survival has been shown many times previously." (PMID 34681753, 2021). "Higher levels of pre- and post-treatment heparanase were noted in oestrogen receptor-negative cancers than in positive ones." (PMID 34070058, 2021). "Proteolytic enzymes, such as matrix metalloproteinases, plasminogen activators and cathepsins, as well as non-proteolytic enzymatic partners, such as heparanase and hyaluron-idases, play key roles in the propagation and metastatic potential of cancer cells." (PMID 33809973, 2021). "The non-enzymatic activity of heparanase—known to be modulated by Sdc-1 expression—induces F3 expression in cancer cells and impacts cancer progression." (PMID 34066023, 2021). "Notably, roneparstat alone did not exert a significant inhibitory effect, probably because the cancer cells used in the study, PANC1, express low levels of heparanase." (PMID 34249755, 2021).
cancer (continued). "Lately, a newly synthesized triazolo–thiadiazoles (4-MMI) has been shown to successfully inhibit enzymatic heparanase activity and heparanase-mediated VEGF gene expression, restraining the ability of carcinoma cells to extravasate through the subendothelial basement membrane." (PMID 35118073, 2021). "Heparanase has been viewed as a promising anti-cancer drug target for almost two decades, but no anti-heparanase therapy has yet reached the clinic." (PMID 31850210, 2019). "Heparanase (HPSE), the only known mammalian endoglycosidase responsible for heparan sulfate cleavage, is a multi-faceted protein affecting multiple malignant behaviors in cancer cells." (PMID 31001480, 2019). "Because heparanase promotes tumorigenesis and is typically not expressed in most normal tissues it is regarded as a promising therapeutic target for cancer patients and other diseases." (PMID 29721203, 2018). "Heparanase was recognised as a potential therapeutic target for cancer in the 1980s, but it was not until 1999 that it was first cloned and expressed." (PMID 30441818, 2018). "MMPs, HPSE, HPSE2 are closely involved in cancer cells’ invasion and metastasis." (PMID 26084486, 2015). "A superexpressão de heparanase-1 e heparanase-2, bem como o aumento da atividade de heparanase-1 e catepsina B no plasma, está associada com o diagnóstico de carcinoma gastrointestinal." (PMID 25351637, 2015). "Transfection of siH1, siH2 or siH3, did not induce the methylation of CpG islands of heparanase promoter in cancer cells." (PMID 22363633, 2012). "Researchers speculate that LMWH’s mechanisms of anti-cancer effects may be through the upregulation of cancer cell apoptosis, inhibition of VEGF, and competition with heparanase for the HS acceptor/interactor that would lead to decreased metastasis through extracellular matrix integrity maintenance." (PMID 40723905, 2025). "The developed enzyme-responsive hydrogel enables controlled drug release triggered by heparin-specific cleavage by heparanase, targeting cancer cells with heparanase overexpression while minimizing the negative effects of premature drug release on normal cells." (PMID 39057463, 2024). "Therefore, the interference with the biogenesis and action of exosomes (possibly via dual heparanase and SDC1 targeting ) could have an excellent impact at multiple levels of cancer hallmarks." (PMID 36980680, 2023). "This cell extravasation-promoting effect of heparanase-1 is not restricted to cancer cells." (PMID 36680276, 2023). "Thus, unlike its deleterious properties in disease states such as cancer and inflammation, heparanase seems to play a favorable role in podocytes, protecting the cells from harsh environmental conditions." (PMID 36293542, 2022). "This may indicate that a high pre-treatment concentration of heparanase may be a negative prognostic factor, thus other cancer-related factors should be taken into account." (PMID 34070058, 2021). "Interestingly, increased expression of heparanase was found in placentas with preeclampsia, where it would enhance the increase of VEGF release and it would influence the invasion of trophoblast, similarly to the invasion of cancer cells." (PMID 31963505, 2020). "It was previously shown that more aggressive tumors exhibit higher heparanase and Syn-1 expression compared to that of nonmetastatic tumors, suggesting that targeting heparanase might improve cancer treatment." (PMID 30922347, 2019). "Increased expression of heparanase in the mammary epithelium of MMTV-driven gene transgenic mice promotes the growth of cancer cells and lung metastasis formation, supporting the notion that increased matrix degradation by heparanase contributes to cancer spreading." (PMID 30237860, 2018). "Notably, elevated levels of heparanase are positively correlated with triggered expression of MMP-9, hepatocyte growth factor (HGF) and vascular endothelial growth factor (VEGF) that are entangled with cancer progression." (PMID 28359266, 2017).
cancer (continued). "Three enzymes – heparanase, Sulf1 and Sulf2 – play crucial roles in regulating HSPG functioning in this compartment and the up- and down-regulation of these proteins in a large variety of cancers demonstrates how important they are in promoting or repressing malignancy." (PMID 25105093, 2014). "In addition, HPSE has independent activity unrelated to enzyme function and directly activates corresponding receptors, increases AKT phosphorylation and participates in malignant tumor metastasis." (PMID 23837057, 2013). "In addition, treatment of cancer cells with the DNMT inhibitor 5-aza-2′-deoxycytidine (5-Aza-CdR) or TSA did not affect heparanase silencing, indicating that DNMTs and HDACs were unlikely to be involved in this process." (PMID 22363633, 2012). "Therefore, it remains unclear whether PHSE is a suppressor or promoter of human cancers, especially for HCC, which is possibly related to the extensive and complex functions of HPSE." (PMID 22952874, 2012). "These factors may explain the contrary reports on HPSE gene in HCC and other cancers." (PMID 22952874, 2012). "Heparanase-inhibiting heparin/HS-mimicking compounds, small molecules, and antibodies are being developed, of which several saccharide-based compounds were and/or are being examined in cancer clinical trials, yet none of the compounds reached the stage of approval for clinical use." (PMID 34199150, 2021). "Nonetheless, the inhibition of heparanase demonstrated that heparan sulfate alone, nor TLR4 stimulation, is not sufficient to favor cancer cell stem-like properties and an active heparanase is always essential." (PMID 39349458, 2024). "The application of therapeutics for cancer treatment has been reported for non-coagulant heparin (SST001) and a phosphomannopentaose sulphate (PI-88) that targets heparanase." (PMID 31261710, 2019). "Thus, in this study, we first examined HPSE inhibitor RDS 3337 effects on human non-cancer neuro-ectodermal cell line RPE-1, which represents a non-transformed alternative to cancer cell lines." (PMID 37508554, 2023). "Combined with the similar findings in EJ and SGC-7901 cells (data not shown), these results suggested that heparanase TSS-targeted shRNA could inhibit the growth, metastasis and angiogenesis of cancer cells in vivo." (PMID 22363633, 2012). "Unexpectedly, the inhibition of heparanase blocked the whole process, strongly supporting the idea that functional heparanase is crucial for activation of TLR4 and heparan sulfate is not sufficient per se to produce the observed effects on cancer cell stemness." (PMID 39349458, 2024).